TIRAP (TIR domain containing adaptor protein)
Description:
Adapter involved in TLR2, TLR4 and RAGE signaling pathways in the innate immune response. Acts via IRAK2 and TRAF-6, leading to the activation of NF-kappa-B, MAPK1, MAPK3 and JNK, and resulting in cytokine secretion and the inflammatory response. Positively regulates the production of TNF (TNF) and interleukin-6 (IL6).
Synonyms: MyD88-2; MAL; wyatt; BACTS1
Tractability: Antibody: UniProt places it where antibodies can reach, with high confidence; its Gene Ontology location is reachable by antibodies, with high confidence. PROTAC: UniProt records ubiquitination sites on it.
Gene: Protein-coding gene on chromosome 11 (126,282,497 to 126,298,845, forward strand). Ensembl gene ENSG00000150455.
Subcellular location: Cytoplasm; Cell membrane; Membrane
Subcellular location (Human Protein Atlas): Cytokinetic bridge; Cytosol; Nucleoplasm
Pathways (Reactome):
Disease: IRAK4 deficiency (TLR2/4); MyD88 deficiency (TLR2/4)
Immune System: ER-Phagosome pathway; MyD88:MAL(TIRAP) cascade initiated on plasma membrane
Gene Ontology:
Molecular function: identical protein binding; molecular adaptor activity; protein binding; protein kinase C binding; protein-macromolecule adaptor activity; signaling adaptor activity; Toll-like receptor 2 binding; Toll-like receptor 4 binding; phosphatidylinositol-4,5-bisphosphate binding
Biological process: 3'-UTR-mediated mRNA stabilization; positive regulation of canonical NF-kappaB signal transduction; positive regulation of ERK1 and ERK2 cascade; positive regulation of interleukin-15 production; positive regulation of interleukin-6 production; positive regulation of interleukin-8 production; positive regulation of JNK cascade; positive regulation of protein-containing complex assembly; positive regulation of toll-like receptor 2 signaling pathway; positive regulation of toll-like receptor 4 signaling pathway; positive regulation of tumor necrosis factor production; response to lipopolysaccharide; TIRAP-dependent toll-like receptor 4 signaling pathway; toll-like receptor 4 signaling pathway; toll-like receptor TLR1:TLR2 signaling pathway; cell surface receptor signaling pathway; cellular response to bacterial lipopeptide; cellular response to lipoteichoic acid; defense response to Gram-positive bacterium; MyD88-dependent toll-like receptor signaling pathway; myeloid cell differentiation; positive regulation of B cell proliferation; positive regulation of chemokine (C-X-C motif) ligand 1 production; positive regulation of chemokine (C-X-C motif) ligand 2 production; positive regulation of interleukin-12 production; and 5 more
Cellular component: cell surface; cytoplasm; extrinsic component of cytoplasmic side of plasma membrane; plasma membrane; cytosol; endocytic vesicle; ruffle membrane; membrane
Genetic constraint (gnomAD): Loss-of-function variants: 20 observed, 20.28 expected, observed/expected ratio (o/e) 0.99, 90% interval 0.69 to 1.43. The upper end of that interval is the gene's LOEUF score, 1.43, which puts it in group 5 of 6, group 1 being the genes least tolerant of losing a copy. Missense variants: 276 observed, 295.58 expected, observed/expected ratio (o/e) 0.93, 90% interval 0.85 to 1.03. Synonymous variants: 125 observed, 126.45 expected, observed/expected ratio (o/e) 0.99, 90% interval 0.85 to 1.15.
Homologues: Orthologues: chimpanzee TIRAP (99% identical), macaque TIRAP (93% identical), dog TIRAP (80% identical), pig TIRAP (80% identical), rabbit TIRAP (79% identical), mouse Tirap (79% identical), rat Tirap (76% identical), guinea pig TIRAP (75% identical), zebrafish tirap (34% identical), tropical clawed frog tirap (32% identical).
Diseases named in the same sentence as TIRAP in open-access papers:
TIRAP is named in the same sentence as 88 diseases in open-access papers, as found by Europe PMC text mining. Sharing a sentence is not in itself a finding about the gene and the disease. The quoted sentences say what the papers report.
tuberculosis (14 papers, 2008 to 2025). A chronic, recurrent infection caused by the bacterium Mycobacterium tuberculosis. "Through differential gene expression analysis, clustering, and enrichment analysis, we identified 13 key biomarkers, including CCL2, SLC11A1, CD209, HLA-DQA1, and TIRAP, which are strongly associated with immune responses in tuberculosis." (PMID 40565607, 2025). "Similar to the findings of this study, the TIRAP SNP has been associated with protection from invasive pneumococcal disease, bacteremia, malaria, and tuberculosis." (PMID 34583337, 2021). "Miao R., Li J., Sun Z., Xu F., Shen H. Meta-analysis on the associationof TIRAP S180L variant and tuberculosis susceptibility." (PMID 35083399, 2021). "Heterozygosity for the MAL/TIRAP variant in the TLRs pathway have been suggested to provide protection against invasive pneumococcal disease, malaria, tuberculosis and chagas disease." (PMID 33868225, 2021). "Furthermore, SNPs in TIRAP are associated to the incidence and severity of several diseases, such as tuberculosis, HIV, and systemic lupus erythematosus (SLE) as well as infections/diseases in which TLR8 is likely to play a role." (PMID 35884781, 2022). "The SNP of TIR domain-containing adaptor protein (TIRAP) S180L appears to confer protection against malaria, tuberculosis, and bacterial diseases." (PMID 28850598, 2017). "To test common and rare TLR variants involved in susceptibility or resistance to infection with Mycobacterium tuberculosis we screened the exons of the genes encoding TLR 1, 2, 4, and the adaptor molecule TIRAP in more than 4500 tuberculosis (TB) cases and controls from Ghana." (PMID 27214039, 2016). "Humans that are heterozygous for the common S180L polymorphism in the Toll-like receptor (TLR) adaptor Mal (encoded by TIRAP) are protected from a number of infectious diseases, including tuberculosis (TB), whereas those homozygous for the allele are at increased risk." (PMID 26885859, 2016). "Heterozygosity for TIRAP S180L has been suggested to be protective not only against malaria but also against bacterial infections including invasive pneumococcal disease, pneumococcal empyema, overall and pneumococcal bacteremia, and tuberculosis." (PMID 19602285, 2009). "The adaptor protein TIRAP mediates down stream signalling of TLR2 and 4, and polymorphisms in the TIRAP gene (TIRAP) have been associated with susceptibility and resistance to tuberculosis (TB) in adults." (PMID 19693265, 2009). "Likewise, the same pattern of TIRAP associations was observed in other Gram-positive or Gram-negative bacterial infections, bacteremia, malaria, and tuberculosis in more than 6,100 individuals." (PMID 30131804, 2018). "TIRAP C558T was associated with susceptibility to TBM as previously reported OR = 2.96 [95% C.I. 1.71–5.11], however, there was no stronger association between TIRAP C558T and TB caused by any unique M. tuberculosis lineage (data not shown)." (PMID 18369480, 2008).
malaria (13 papers, 2009 to 2025). Malaria is a serious and sometimes fatal disease caused by a parasite that commonly infects a certain type of mosquito which feeds on humans. "This study aimed to evaluate the association between polymorphisms in TLR1, TLR4, TLR7, TLR8, TLR9 and TIRAP and the clinical manifestations of malaria caused by P. vivax in a population from the Amazon region of Pará, Brazil." (PMID 40963451, 2025). "A particular TIRAP variant was correlated with mild malaria amongst people living in Iran, Gambia, Vietnam, and Kenya." (PMID 25157202, 2014). "An SNP mutation in the TIRAP gene (rs8177374; S180L) has been associated with both protection against malaria and susceptibility to the development of mild malaria, but the association of the TIRAP gene polymorphism with malaria remains controversial." (PMID 23316245, 2012). "Surprisingly, however, we detected the heterozygous TIRAP S180L variant in only one (0.1%) out of 1095 individuals from malaria holoendemic Ghana." (PMID 19602285, 2009). "Therefore, this study aimed to analyse the potential influence of variants of TLR1, TLR4, TLR7, TLR8, TLR9 and TIRAP on the clinical manifestations of malaria caused by P. vivax in the Amazon region of Brazil." (PMID 40963451, 2025). "This study was planned to make a further contribution to solving the problem of the real role of the most common polymorphisms of TLR4, TLR9, TIRAP and FCGR2A in modulating the risk of malaria and disease severity." (PMID 22691414, 2012). "We assessed the TIRAP S180L variant by melting curve and RFLP analysis in 1095 delivering women from malaria-endemic Ghana, as well as in a further 1114 individuals participating in case control studies on sepsis and leprosy in Germany, Turkey and Bangladesh." (PMID 19602285, 2009). "In this study, contrary to what was reported by some authors, no protective effect of TIRAP Ser180Leu heterozygosity on susceptibility to and severity of malaria was found." (PMID 22691414, 2012). "This study was planned to make a further contribution to solving the problem of the real role of the most common polymorphisms of TLR4, TLR9, TIRAP and FCGR2A genes in modulating the risk of malaria and disease severity in children from Burundi, Central Africa." (PMID 22691414, 2012). "In an attempt to verify these broad and evolutionary important effects, we screened for TIRAP S180L in a Ghanaian population exposed to holoendemic malaria transmission, and examined the role of the SNP in Caucasian and Asian patients affected by sepsis or leprosy." (PMID 19602285, 2009). "While the TLR system has been shown to be critically involved in susceptibility to and manifestation of malaria, we found a very low frequency of the S180L mutation in the TLR downstream mediator TIRAP in a highly endemic region arguing against a major role of this SNP in malaria." (PMID 19602285, 2009). "The current immunogenetic study was designed to analyse the key components of innate immunity, TLRs and TIRAP (Toll-interleukin-1 receptor domain-containing adaptor protein), also known as MAL (MYD88 adaptor-like), in Iranian patients with mild malaria." (PMID 21457584, 2011). "The overall data seem to indicate that none of the SNPs of TLR4, TIRAP and FCGR2A genes studied, assessed in Burundian children, play a role in modulating susceptibility to malaria and disease severity in this population." (PMID 22691414, 2012). "TLR9 T1237C seems to condition susceptibility to malaria in Burundian children but not its severity, whereas none of the assessed SNPs of TLR4, TIRAP and FCGR2A seem to influence susceptibility to malaria and disease severity in this population." (PMID 22691414, 2012).
Sepsis (13 papers, 2009 to 2025). Sepsis is defined as life-threatening organ dysfunction caused by a dysregulated host response to infection. "In conclusion, we reported for the first time that two tag SNPs in the TIRAP gene contribute to increased risk of sepsis-associated ALI in Han Chinese population." (PMID 21118491, 2010). "Remarkably, homozygous TIRAP 180L tend to increase the risk of sepsis in the German study (P = 0.04)." (PMID 19602285, 2009). "In addition, TIRAP was also involved in defending against sepsis- or bacterial-associated acute lung injury." (PMID 31207932, 2019). "In contrast, the homozygous TIRAP 180L genotype was significantly more frequent in patients, (4.5 versus 1.1%, P = 0.04), indicating this genotype to potentially be a risk factor for developing sepsis." (PMID 19602285, 2009). "In contrast, in sepsis TIRAP 180L homozygosity appears to be a risk factor for disease." (PMID 19602285, 2009). "The frequencies of both genetic variations in TLR4 and TIRAP/Mal have been recently studied worldwide in a comparative fashion, and it has been proposed that differences between regional populations can be attributed to selective pressure due to differences in sepsis susceptibility." (PMID 20525286, 2010). "TIRAP expression in the early stages of sepsis was in accordance with the amplification in the expression of TLR-9, indicating a possible correlation." (PMID 40076895, 2025). "In an interesting development, peptides derived from MyD88- or TLR-interacting surface patches of TIRAP blocked LPS-mediated signal transduction in mouse models of sepsis and rheumatoid arthritis." (PMID 29434596, 2018). "In recent years, TIRAP has been investigated intensively because of its importance in the signal transduction pathway of TLR4—the principal agent responsible for sepsis, an endotoxin-induced deadly autoimmune disease." (PMID 29434596, 2018). "In summary, our studies describe a novel association between common genetic polymorphisms in sequential elements of the endotoxin recognition system (TLR4 and the intracellular signaling adaptor TIRAP/Mal) and the course of sepsis and pneumonia." (PMID 20525286, 2010). "For risk associations with severe sepsis we compared the SNP carriers (41 heterozygous TLR4, and 10 homozygous and 75 heterozygous carriers of the TIRAP/Mal-SNP) with WT-patients (n = 240)." (PMID 20525286, 2010). "PCR analysis revealed the significant up-regulation of MyD88 and TIRAP during sepsis." (PMID 40076895, 2025). "Furthermore, TIRAP was amplified in the septic groups and a significant difference was observed between 48 h and 72 h of the onset of sepsis." (PMID 40076895, 2025). "Another study found that protein expression levels of TLR4 and its adaptor TIRAP (TIR domain containing adaptor protein) correlated strongly with sepsis severity, suggesting that expression assays may be more clinically relevant than genotyping alone in some contexts." (PMID 41154281, 2025). "The expression of PD-1; PD-L1; TLR-5, -6, and -9; MYD88; IRAK1; TIRAP; and NFkB was quantified by RT-PCR at 24, 48, and 72 h after CLP-induced sepsis." (PMID 40076895, 2025). "In animal sepsis models, multiple molecules such as TAK-242, eritoran, and TIRAP decoy peptides block TLR4 signaling at different stages through various modes of action, thereby enhancing the chances of survival for septic mice and lowering cytokine levels." (PMID 39606629, 2024). "In our study populations with a relative high prevalence of the TIRAP S180L, we found a trend but no significant protection of heterozygosity in sepsis and leprosy." (PMID 19602285, 2009).
bacteremia (6 papers, 2009 to 2021). "Conversely, enhancing TLR2-mediated host defense may hasten clearance of SE bacteremia; consistent with protection against bacteremia afforded by hypermorphic alleles of TIRAP, a signaling molecule downstream of TLR2." (PMID 20404927, 2010).
gastric cancer (5 papers, 2019 to 2023). A primary or metastatic malignant neoplasm involving the stomach. "In fact, it has been reported that aberrant expression of TIRAP leads to the development of multiple tumors including lymphocytic leukemia, gastric cancer, colorectal cancer, and so on." (PMID 31207932, 2019). "We collected gastric cancer cell line MGC-803 and performed PCR experiments to verify the expression of the key gene TIRAP." (PMID 36428916, 2022). "TIRAP is a member belonging to the TLR/IL-1R family, and an aberrant expression of TIRAP could induce tumorigenesis including gastric cancer, colorectal cancer, and lymphocytic leukemia." (PMID 34804944, 2021).
pneumonia (5 papers, 2010 to 2021). An acute, acute and chronic, or chronic inflammation focally or diffusely affecting the lung parenchyma, caused by an infection in one or both of the lungs (by bacteria, viruses, fungi, or mycoplasma.). "Most likely, the contribution of the alleles ofgenes TLR2 and TIRAP to CAP predisposition is determinedby pneumonia etiology." (PMID 35083399, 2021). "Due to the attenuation of neutrophil sequestration and the production of MIP-2, TNF-, IL-6, and LIX, Toll/IL-1R Domain-Containing Adaptor Protein (TIRAP), has been reported to play a critical role in pneumonia caused by K. pneumoniae." (PMID 34737734, 2021). "During a P. aeruginosa-induced pneumonia, it was evident that TIRAP is not required for neutrophil infiltration, LIX production, and bacterial clearance." (PMID 34737734, 2021).
COVID-19 (4 papers, 2021 to 2024). A disease caused by infection with severe acute respiratory syndrome coronavirus 2. "Our findings demonstrated that carriage of the TIRAP polymorphism rs8177374 was significantly associated with lower mortality in COVID-19." (PMID 34995294, 2022). "This study shows that carriage of TIRAP polymorphism rs8177374 could be associated with a significantly lower mortality in COVID-19." (PMID 34995294, 2022). "We investigated whether genetic polymorphisms in candidate genes ACE2, TIRAP, and factor X are associated with clinical outcomes in COVID-19." (PMID 34995294, 2022). "This TIRAP polymorphism may be an important predictor in the outcome of COVID-19 and external validation is necessary to consider this association." (PMID 34995294, 2022). "In conclusion, this study shows that carriage of the TIRAP polymorphism rs8177374 could be associated with lower mortality in COVID-19." (PMID 34995294, 2022). "This TIRAP polymorphism may be an important predictor in the outcome of COVID-19." (PMID 34995294, 2022). "We observed that platelets from patients with COVID-19 showed a greater phosphorylation of TIRAP than HS." (PMID 34092777, 2021). "To examine the role of LPS on platelet activation in patients with COVID-19, we evaluated the phosphorylation of TIRAP, that is marker of TLR4 activation." (PMID 34092777, 2021). "Furthermore, the immunocomplex formation of TIRAP with MyD88, called myddosome, that is required for TLR4 signal transduction, was significantly higher in platelets from patients with COVID-19 compared with HS." (PMID 34092777, 2021).
lung carcinoma (4 papers, 2019 to 2025). "Six key immune genes (TLR2, TLR4, CCR7, IL18, TIRAP and FOXP3) showed cell‐type specific expression patterns in the lung cancer microenvironment." (PMID 41319095, 2025). "Our analysis identified six key immune regulatory genes (TLR2, TLR4, CCR7, IL18, TIRAP and FOXP3) that show differential expression between lung cancer and normal tissues and demonstrate potential prognostic value." (PMID 41319095, 2025). "It was also found that phycocyanin, a food-derived inhibitor, could inhibit TIRAP in NSCLS cells and exert an antiproliferation effect through downregulating TIRAP/NF-kB activity in lung cancer." (PMID 34804944, 2021).
systemic lupus erythematosus (4 papers, 2013 to 2023). An autoimmune multi-organ disease typically associated with vasculopathy and autoantibody production. "Studies have found that the TIRAP single nucleotide polymorphism is also a protective factor in systemic lupus erythematosus." (PMID 38028622, 2023). "One of the intent elementness of the study conducted by Castiblanco was to investigate the influence of the functional TIRAP (MAL) S180L polymorphism on the autoimmune disease systemic lupus erythematosus (SLE) and proved that it is a specific factor for SLE." (PMID 24312583, 2013).
viral infection (4 papers, 2013 to 2020). "Following viral infection, TLRs predominantly employ either of two pathways: the MyD88-dependent pathway or the TRIF-dependent pathway, via different TIR-domain containing adaptor proteins, such as MyD88, Mal (MyD88 adaptor-like protein), TIRAP (TIR-associated protein), TRIF and TRAM." (PMID 29558453, 2018).
colorectal cancer (3 papers, 2019 to 2022). A primary or metastatic malignant neoplasm that affects the colon or rectum. "TIRAP polymorphisms have been studied in the context of lymphoma, glioma, and colorectal cancer, as we previously indicated; however, we were unable to locate any studies on cervical cancer." (PMID 36011276, 2022).